MIR573 (microRNA 573)
Synonyms: hsa-mir-573; MIRN573; mir-573
Gene: MicroRNA gene on chromosome 4 (24,520,192 to 24,520,290, reverse strand). Ensembl gene ENSG00000207697.
Gene Ontology:
Biological process: miRNA-mediated post-transcriptional gene silencing
Cellular component: RISC complex
Diseases named in the same sentence as MIR573 in open-access papers:
MIR573 is named in the same sentence as 3 diseases in open-access papers, as found by Europe PMC text mining. Sharing a sentence is not in itself a finding about the gene and the disease. The quoted sentences say what the papers report.
melanoma (1 paper, 2021). A malignant, usually aggressive tumor composed of atypical, neoplastic melanocytes. "Moreover, MIR-573 reduction was demonstrated to be essential in melanoma initiation and progression." (PMID 34073305, 2021).
MIR573 also shares sentences with these, for which no sentence is quoted: cervical cancer (1 paper); prostate carcinoma (1).